ESR1 (estrogen receptor 1)
Diseases named in the same sentence as ESR1 in open-access papers (continued):
Sharing a sentence is not in itself a finding about the gene and the disease.
ovarian carcinoma (continued). "Kaplan–Meier survival analysis revealed a longer progression-free survival (PFS) and overall survival (OS) in ovarian cancer patients with low PAPSS1 expression and high ESR1 expression than those with low ESR1 and high PAPSS1." (PMID 37684671, 2023). "An inverse correlation of the gene expression between ESR1 and PAPSS1 was revealed in ROC plotter datasets of ovarian cancer." (PMID 37684671, 2023). "However, another study showed that appropriate concentrations of CDCA and DCA can reduce ESR1 expression in ovarian cancer cells by almost 90%, indicating that CDCA may reduce proliferation by inhibiting ESR1 expression in ectopic endometrial cells through targeted effects." (PMID 36071850, 2022). "In this paper, we explore the expression of four estrogen signaling pathway mediators, ESR1, ESR2, PELP1 and SRC kinase in ovarian cancer patients." (PMID 34207568, 2021). "The results of the HOUP hub genes confirmed that the expression levels of TNF, ESR1, CDK1, CXCR4 and MUC1, indicating these 5 hypomethylated genes were activated in ovarian cancer development." (PMID 32192517, 2020). "It has a sequence that regulates ESR1 and ESR2 genes, and it is still among the main candidate genes for endometriosis and ovarian cancer." (PMID 32143537, 2020). "This point was already addressed by others who demonstrated that downregulation of DNMT3A and DNMT3B led to regulation of ESR1 or ESR2 via promoter DNA aberrant methylation in acute myeloid leukemia, endometriosis, prostate and ovarian cancer." (PMID 23626723, 2013). "Strong nuclear ESR1 protein expression was observed in breast, endometrial, and ovarian cancers, but not in other cancers." (PMID 37240447, 2023). "Interestingly, this miRNA was also found as a regulatory element for genes such as PTEN, SMAD4, ESR1, NRG1, etc., in the miRWalk database for ovarian carcinoma." (PMID 36899893, 2023). "In addition, an inverse correlation of the gene expression between ESR1 and PAPSS1 was observed in ROC plotter datasets of ovarian cancer." (PMID 37684671, 2023). "TNF, ESR1, MUC1 are HOUP genes, suggesting a potential role in ovarian cancer progression." (PMID 32192517, 2020). "Hub genes including TNF, ESR1, MUC1 and FOXO1 might be potential targets for diagnosis or treatment of ovarian cancer in an epigenetic approach, TNF, ESR1 and FOXO1 may serve as potential markers for ovarian cancer prognosis evaluation." (PMID 32192517, 2020). "The ESR1-driven subset of E2 actions may be partially or entirely mediated by GREB1, which drives proliferation and tumour growth in mouse models of ovarian cancer." (PMID 29973689, 2018). "Given that GREB1 induction is dependent on E2 signalling, we used the CAG-TAg murine model of ovarian cancer to determine the impact of Esr1 deletion on survival of mice with and without exogenous E2 treatment." (PMID 29973689, 2018). "Our previous report showed that ESR1 mRNA expression is up-regulated 51-fold (P<0.001) in ovarian cancer in laying hens while there is little or no detectable ESR1 protein in normal ovaries." (PMID 25020046, 2014). "Thus, we predict that E2F1 negatively regulates HSD17B2 in ovarian cancer and that reduced HSD17B2 results in an excess of estradiol, which in turn activates cell-proliferation genes through the activation of ESR1." (PMID 22548828, 2012). "Similarly, genes shared between endometriosis, uterine fibroids, ovarian cancer, migraine and depression (RHOA, FOXP1, ESR1, WNT4, GREB1, FSHB), and endometriosis, migraine and asthma (IGF1, SMAD3, MFHAS1), were enriched in hormone receptor signalling and inflammation pathways, respectively." (PMID 37159502, 2023). "TNF, ESR1, MUC1 and FOXO1 are our candidate genes that might take part in ovarian cancer progression in an epigenetic approach, TNF, ESR1 and FOXO1 may serve as potential markers for ovarian cancer prognosis evaluation." (PMID 32192517, 2020).
ovarian carcinoma (continued). "GREB1 and ESR1 are co-expressed in normal female reproductive tissues, whereas GREB1 is present, with or without ESR1, in the majority of ovarian cancers of all major histological subtypes." (PMID 29973689, 2018). "Additionally, we investigated the correlation of estrogen-related pathway genes (ESR1, ESR2, PELP1, and c-SRC) with hsa-miR-21 and hsa-miR-145 in non-affected ovary and ovarian cancer." (PMID 40362695, 2025).
Obesity (306 papers, 2005 to 2026). Accumulation of substantial excess body fat. "ESR1-specific signaling in adipocytes has been shown to promote insulin sensitivity, and reductions in ESR1 have been linked to obesity and insulin resistance." (PMID 39833659, 2025). "ESR1 is one of estrogen receptor gene families and is significantly associated with lipid metabolism and severe obesity." (PMID 36297109, 2022). "Our finding regarding an inverse association between the ESR1 expression in adipose tissue and obesity was consistent with previous human studies." (PMID 35682668, 2022). "Although we demonstrated that genetic variants on ESR1 and PPARg locus are associated with severe obesity (BMI > 35) in Han Chinese individuals, their associations with mild to moderate obesity (BMI in the range of 27.0 to 34.9) were not tested." (PMID 36297109, 2022). "The present results also found that rs712221 on the ESR1 gene was not only associated with severe obesity but also with mild to moderate obesity with BMI in the range of 27–35 in Taiwanese population." (PMID 36297109, 2022). "We found that obesity was associated with a significant decrease in ESR1 and ESR2 mRNA levels in adipose tissue; however, the effect was depot- and gender-specific." (PMID 35682668, 2022). "ESR1 gene polymorphism exhibited a reduced BMI in male and female subjects and also known to attenuate the risk of obesity." (PMID 33669862, 2021). "It is reported that the C-allele of ESR1-PvuII and its associated genotypes and haplotypes are inversely and consistently associated with obesity." (PMID 32682401, 2020). "Oestrogen resistance induced obesity was first described in a man with an inactivating mutation of the ESR1." (PMID 30181488, 2018). "SNPs from genes associated with alcohol dependence (ESR1) and obesity traits (RGS7, NRG3 and ESR1) were observed among Western reported dietary pattern score-associated SNPs." (PMID 28644415, 2017). "A human male with an ESR1-null mutation had insulin resistance, impaired glucose tolerance, obesity and increased height." (PMID 27453734, 2016). "A human male with an ESR1-null mutation had insulin resistance, impaired glucose tolerance and obesity." (PMID 26370976, 2015). "Among 5 selected polymorphisms (rs9594738 of RANKL, rs17066364 of NUFIP1, rs7227401 of OSBPL1A, and rs1856057 and rs2982573 of ESR1) analyzed, 2 polymorphisms (rs9594738 and rs17066364) were associated with obesity-related traits." (PMID 23300848, 2012). "Expression of the mitochondrial gene ESR1 in adipocytes, which is responsible for encoding estrogen receptor α (ERα), may be dependent on obesity." (PMID 38920999, 2024). "However, subgroup analysis revealed that obesity was associated with significant downregulation of ESR1 mRNA levels in the VAT of the obese premenopausal women compared with the non-obese controls (p < 0.0001)." (PMID 35682668, 2022). "Therefore, further studies, including single-cell analyses, are required to verify the role of DNA methylation in regulating obesity and weight-loss-associated changes in ESR1 and ESR2 transcriptional activity in adipose tissue." (PMID 35682668, 2022). "Altered ESR1 function is associated with obesity and metabolic dysfunction in humans and it was reported to be critical for regulation of lipid metabolism in mice where it regulates the synthesis of cholesterol transport proteins, enzymes for lipoprotein remodeling, and receptors for cholesterol." (PMID 36510146, 2022). "Adipose tissue produces estrogen, which might indicate an underlying relationship between ESR1 and obesity-related genes." (PMID 35795061, 2022). "Animal studies reported that male and female ESR1 gene knockout mice developed features of the metabolic syndrome (MetS) including obesity caused by impaired fatty acid oxidation, glucose intolerance, and impaired insulin sensitivity, thus revealed the critical role of ESR1 in metabolic homeostasis." (PMID 31293826, 2019).
Obesity (continued). "In conclusion, all together, our results suggest the possibility that the persistently high E2 levels associated with obesity leads to ESR1 downregulation in adipocytes and reduced E2 sensitivity, which in turn results in attenuated fat mass loss in response to T therapy." (PMID 30181488, 2018). "Thus, ESR1 KO mice demonstrate genera in their fecal microbiome previously associated with obesity." (PMID 26971397, 2016). "Studies on associations in females have been reported for the estrogen receptor (ESR1 or ESR2) with MetS or its components, particularly with obesity and dyslipidemia; these associations might be explained by single nucleotide polymorphisms (SNPs) in the ESR1 gene, as reported by some studies." (PMID 26370976, 2015). "It is also important to note that the discrepancy between ESR1 gene and protein expression in the obesity comparisons raises important questions about posttranscriptional regulation and protein stability." (PMID 39833659, 2025). "ESR1:ESR2 gene expression was negatively associated with age, obesity markers (eg, BMI, WHR, body fat percentage), and fasting glucose." (PMID 39833659, 2025). "ESR1 gene expression inversely correlated with age, obesity markers (eg, BMI, WHR, body fat percentage), and markers of hyperglycemia and insulin resistance (eg, HbA1c, HOMA-IR, insulin) (P < .05)." (PMID 39833659, 2025). "Since adipocyte Esr1 has emerged as a novel anti-inflammatory molecule in obesity, we focus on Esr1 as the major methylation target during diet-induced obesity in this study." (PMID 40666843, 2025). "In our study, we observed reduced ESR1 gene expression in SAT from men with obesity, along with a trend for lower ESR1 gene and protein expression in SAT from men with T2D compared to those without T2D." (PMID 39833659, 2025). "ESR1 gene expression levels were lower in men with obesity than in lean men and men with overweight (P < .05), while ESR2 gene expression levels were not affected by obesity status." (PMID 39833659, 2025). "This is consistent with a previous study showing that ESR1 gene expression is reduced in SAT from men with obesity, but unaltered by T2D." (PMID 39833659, 2025). "ESR1:ESR2 gene expression ratio was lower in participants with obesity compared to lean individuals (P < .05)." (PMID 39833659, 2025). "ESR1 expression in adipose tissues was negatively correlated with obesity and genes related to mitochondrial metabolism and metabolic health markers." (PMID 35267929, 2022). "Our results also showed that ESR1 directly regulates the obesity-differential gene MMAA to improve the prognosis of HCC patients." (PMID 35795061, 2022). "The presence of ESR1 mutations is associated with obesity-independent EC, and patients with ESR1 LBD mutations tend to have a worse prognosis than patients with wild-type ESR1 tumors." (PMID 35629078, 2022). "Even though the association between the decline in ESR1 and ESR2 expression in adipose tissue and the incidence of obesity has been postulated for some time, little is still known about the molecular mechanisms leading to these phenomena." (PMID 35682668, 2022). "As ESR1 promotes the development of secondary sexual characteristics in female animals, we demonstrate a novel function for it to directly regulate the obesity-differential gene MMAA and affect the cancer biological behavior of HCC." (PMID 35795061, 2022). "Estrogen receptor alpha (ESR1) regulates angiogenesis of adipose tissue via VEGFA, and ESR1-deficient mice are exposed to insulin resistance and obesity." (PMID 35052852, 2022). "Studies have shown that the ESR1 gene knockout led to weight gain, obesity, and lipid deposition in rats." (PMID 36506575, 2022). "In animal studies, male and female ESR1 gene knock-out mice have acquired metabolic syndrome characteristics including obesity due to decreased fatty acid oxidation, impaired glucose tolerance, and reduced insulin sensitivity." (PMID 35627115, 2022).
Obesity (continued). "Polymorphisms in genes encoding ERα (ESR1) and ERβ (ESR2) were associated with the risk of obesity and metabolic syndrome; however, the associations were population-specific." (PMID 35682668, 2022). "What distinguished the obesity-related changes in ESR2 expression compared with ESR1 in our study was that the decrease in ESR2 gene expression referred to visceral and subcutaneous adipose tissue depots." (PMID 35682668, 2022). "In contrast, data on the influence of weight status on ESR2 mRNA levels in adipose tissue are scarce; however, our study suggested that the obesity and weight-loss-related changes in ESR2 expression in SAT mimic those observed in the case of ESR1." (PMID 35682668, 2022). "RPS6KB1 (an AMPK responsive gene for protein synthesis and cell growth), estrogen receptor α (encoded by the ESR1 gene) and its target gene GATA3, were significantly downregulated in rFNAs from premenopausal women with obesity." (PMID 34485137, 2021). "On the other hand, prostaglandin-endoperoxide synthase 2 (PTGS2), cyclin D1 (CCND1), and TFF1 (an ESR1 target gene) were elevated in rFNAs from postmenopausal women with obesity." (PMID 34485137, 2021). "The generation of Esr1−/− and Cyp19a1−/− mice revealed that ESR1 and aromatase deficiency leads to the development of obesity and insulin resistance." (PMID 33430527, 2021). "We here demonstrated associations of ESR1 and ESR2 polymorphisms with MetS and related components, especially obesity, and lipid and glucose metabolism, in postmenopausal Chinese Han females." (PMID 30217154, 2018). "Lastly, obesity networks (e.g., transcripts including Retn, Lpl, Lep, Esr1, Lipc, Hsd11b1, Gpt, Lipe, Vldlr, and Il6, among others, fold change −1.042, P < 0.05) were also decreased by 4% (1.04-fold)." (PMID 28446880, 2017). "For instance, ESR1 KO mice demonstrate obesity, adipocyte hyperplasia and hypertrophy, insulin resistance, and impaired glucose tolerance." (PMID 26971397, 2016). "In this report we analyse ESR1 and ESR2 gene single nucleotide polymorphisms (SNPs) for association with obesity." (PMID 18053221, 2007). "In this report we analyse polymorphisms covering most of the common haplotype variation in the ESR1 and ESR2 genes for association with obesity in two large cohorts of Swedish Caucasians." (PMID 18053221, 2007). "Consistent with this, our previous work demonstrated that DNMT1/3A-mediated methylation at the Esr1 promoter in adipocytes suppresses estrogen receptor expression, thereby promoting adipose tissue inflammation and contributing to obesity-induced insulin resistance in female mice." (PMID 41596507, 2026). "Further, we have also shown that DNMT1/3A-mediated methylation at Esr1 promoter played an important role in regulating adipose inflammation, which may contribute to obesity-induced insulin resistance." (PMID 41596507, 2026). "Our study demonstrates that DNA methylation at Esr1 promoter plays an important role in regulating adipose inflammation, which may contribute to obesity-induced insulin resistance." (PMID 40666843, 2025). "Additionally, ESR1 gene expression was negatively correlated with markers of obesity (eg, BMI, WHR), impaired glycemia, and insulin resistance (eg, HbA1c, HOMA-IR)." (PMID 39833659, 2025). "In this study, we tested the hypothesis that epigenetic regulation at the Esr1 promoter by HFD feeding, which often causes obesity, mediates adipocyte inflammation and chemotaxis, leading to obesity-induced insulin resistance and type 2 diabetes." (PMID 40666843, 2025). "In the present study, we tested the hypothesis that DNA methylation at estrogen receptor α (Esr1) promoter mediates adipocyte inflammation and chemotaxis, leading to obesity-induced insulin resistance." (PMID 40666843, 2025). "Our study demonstrated that DNA methylation at Esr1 promoter played an important role in regulating adipose inflammation, which may contribute to obesity-induced insulin resistance." (PMID 40857119, 2025).